MIR6813 (microRNA 6813)
Synonyms: hsa-mir-6813
Gene: MicroRNA gene on chromosome 20 (64,076,955 to 64,077,010, reverse strand). Ensembl gene ENSG00000274034.
Homologues: Orthologues: chimpanzee MIR6813 (100% identical).